CXCR2 (C-X-C motif chemokine receptor 2)
Diseases named in the same sentence as CXCR2 in open-access papers (continued):
Sharing a sentence is not in itself a finding about the gene and the disease.
tumor (continued). "In the correlation analysis of MB purity and the immune microenvironment, three genes related to immunity, namely, CD8A, CXCR2, and TNFRSF14, were negatively related to tumor purity." (PMID 34925437, 2021). "CXCR2 with its ligands shows powerful chemotaxis of neutrophils or myeloid-derived suppressor cell (MDSC) and is related to tumor angiogenesis, progression and chemoresistance." (PMID 33814009, 2021). "Inhibition of CXCR2 and CCR2 in this model reversed infiltration of MDCSs and tumor progression and increased T-cell influx." (PMID 34203869, 2021). "On the contrary, several sets of chemokines and their receptors, such as CCR2/CCL2, CXCR2/CXCL5, and VEGF, have been reported to promote tumor progression in other tumors by enhancing immunosuppressive M2-TAM and MDSC function." (PMID 34200100, 2021). "Initial studies demonstrated that recombinant as well as tumor cell line-derived CXCL1 induced chemoattraction in vitro and IFN-γ secretion of CXCR2-engineered T cells." (PMID 33680923, 2020). "In murine tumor models, IL-17 promotes MDSCs tumor infiltration, in a CXCL5/CXCR2-dependent manner, and enhances the immunosuppressive activity of MDSCs." (PMID 32849585, 2020). "Inhibition of CXCR2 altered neutrophil/MDSC recruitment and enhanced T cell infiltration into the tumor site." (PMID 32509781, 2020). "CXC-receptor-2 (CXCR2) and its ligands (CXCL1-3,5-8) are one such group of inflammatory chemokines considered pro-tumor factors in multiple cancer types." (PMID 33049964, 2020). "Upon activation by tumor cells, platelets secrete CXCL5 and CXCL7 chemokines to recruit CXCR2-positive neutrophils." (PMID 33414786, 2020). "The primary immune function of CXCR2 is the regulation of neutrophil and MDSC migration and recruitment to inflammation including tumor sites." (PMID 32509781, 2020). "In a breast cancer mouse model, CXCR2+ MDSCs promoted tumor growth and metastasis by secretion of IL-6 and modulation of CD4+ and CD8+ T cell recruitment to the tumor site." (PMID 32509781, 2020). "In head and neck and lung tumor-bearing mice, treatment with SX-682, a small inhibitor of both CXCR1 and CXCR2, resulted in abrogation of tumor infiltrating MDSCs." (PMID 33203092, 2020). "Treatment with the CXCR2 inhibitor, SB265610, plus the anti-human VEGF antibody, bevacizumab, significantly reduced tumor growth of MDA-MB-231 xenografts compared to bevacizumab or SB alone." (PMID 33520697, 2020). "Since several types of MDSCs express CXCR2, intratumor production of CXCL5 and CXCL8 is important to migration of MDSCs in the tumor microenvironment." (PMID 32707850, 2020). "High expression of FMNL1, with the help of HDAC1, upregulates CXCR2 to trigger EMT process and to facilitate cell migration and tumor metastasis in ccRCC." (PMID 33324547, 2020). "CXCR2 is a receptor for CXCL1, 2, and 3, and IL8 that has been shown to have a profound effect on tumor epithelial interactions with stromal cells." (PMID 33520697, 2020). "Reversely, the chemokine receptor CXCR2 and its ligands CXCL1, CXCL2, and CXCL5 play an important role in homing of neutrophils to cancer cells to limit tumor growth." (PMID 33105656, 2020). "Combined treatment of MDA-MB-231 xenografts using a CXCR2 inhibitor, SB265610, and an anti-VEGF antibody, bevacizumab, showed significant anti-tumor effects both on size of the tumor and reduction in neoangiogenesis." (PMID 33520697, 2020). "By targeting CXCR2, MDSC populations were reduced and reported to decrease metastasis, promote T-cell infiltration into the tumours, improve anti-PD1 therapy, and extend survival in pancreatic cancer." (PMID 32121014, 2020). "In a tumor setting, certain oxysterols (i.e., 22- and 24-OHC) promoted immunosuppression by enhancing the recruitment of pro-tumoral neutrophils in a CXCR2-dependent manner." (PMID 32823961, 2020).
tumor (continued). "It is worth noting that CSF1R inhibitor combined with CXCR2 antagonist intervention can block PMN-MDSC infiltration of tumor tissues, and has a strong tumor treatment effect." (PMID 33224886, 2020). "Therapeutic targeting of the IL-1β/IL-1R or the CXCL1/CXCR2 circuits in an adjuvant setting circumvents chemotherapy resistance in breast cancer patients, and the pre-clinical model of IRISOE TNBC tumor." (PMID 31014367, 2019). "IL-8 is an important multifunctional cytokine that not only participates in various inflammatory diseases, but also mediates tumor migration, invasion and angiogenesis by binding CXCR1 and CXCR2." (PMID 31684995, 2019). "Consistent with this idea the small molecule CXCR2 antagonist, AZD5069 effectively blocked the influx of TAN into both the intratumoral and peritumoral areas at early time points after tumor cell inoculation (left columns, 2–3h)." (PMID 31293583, 2019). "We also mention CXCR2 and CXCR3 as important mediators or tumor angiogenesis, given their distinct roles with angiogenic and angiostatic chemokines, respectively." (PMID 30800123, 2019). "Next, we performed staining for CD31 and LYVE-1 to study tumor invasion into the vein and lymph vessels, respectively, because invasion of PDAC cells was inhibited by CXCR2 inhibitor in vitro." (PMID 30659170, 2019). "Neutrophils and myeloid derived suppressor cells (MDSCs) are recruited to the tumor through ligands for CCR2, CCR3, CXCR1, CXCR2, and CXCR4." (PMID 30873179, 2019). "In our previous study concerning the measurement of concentrations of a specific receptor for CXCL-8 (CXCR-2), we found statistically significant differences only between serum CXCR-2 levels and tumor differentiation (G factor)." (PMID 30820705, 2019). "Ablation of CXCR2 strongly reduced immune cell recruitment to the PDAC and led to a T-cell-dependent suppression of tumor growth." (PMID 31561620, 2019). "The chemokines CXCL1, CXCL2, CXCL5, CXCL6, and CXCL8 secreted from tumor cells attract neutrophils in the blood to the tumor microenvironment via CXCR1 and CXCR2 on the surface of neutrophils." (PMID 30736371, 2019). "Interleukin-8 (IL-8), also known as CXCL8, which is secreted by tumor and inflammatory cells, promotes tumor migration, invasion, angiogenesis, and metastasis by binding with its receptors, CXCR1 and CXCR2." (PMID 31684995, 2019). "We demonstrate here that CXCR2-expressing CAR T-cells migrate more efficiently towards IL-8 and towards tumor conditioned media that contains this cytokine." (PMID 31091832, 2019). "Neutrophils recruited to the tumor via CXCR2 can aid tumor progression and inhibition of CXCR1 and CXCR2 has shown promise in mouse models and human cancers." (PMID 31474989, 2019). "In contrast, although A20-28z CXCR2+ CAR T-cell treated mice had similar initial response rates at day 18, tumor control was significantly improved from day 26 onwards compared to A20-28z-treated mice." (PMID 31091832, 2019). "Furthermore, 4T1 cells that express CXCR2 have characteristics of CSCs, including a low proportion of CXCR2-positive cells (~1%), hypoxia, elevated expression of CSC-associated mRNA, increased tumor spherule formation, tumor xenografts, resistance to radiotherapy and chemotherapy." (PMID 31788042, 2019). "Alyssa D. Gregory and A. Mc Garry Houghton suggest two different possible strategies: (a) targeting the “CXCL-8/CXCR-1/CXCR-2 axis,” thereby entirely exhausting TANs or (b) targeting specific PMN-derived substances able to induce tumor growing." (PMID 31799175, 2019). "Tumor-expressed CXCL5 in melanoma has also been found to drive tumor lymphangiogenesis and lymphogenous metastasis through CXCR2 expressed on LECs." (PMID 31105685, 2019). "(c) Expression of CCR2, CCR4, CCR5, CCR7, CXCR1, CXCR2 and CXCR7 on tumor-infiltrating mast cells by gating on CD45+CD117+FcεRI+ cells." (PMID 30808413, 2019).
tumor (continued). "Other stroma-targeted strategies include CSF-1R, CXCR1, CXCR2, and CCR2/CCR5 blockades, which inhibit the trafficking and recruitment of myeloid cells such as macrophages into the tumor." (PMID 31540435, 2019). "Heterozygous knockout of Cxcr2 in PKF mice (PKF2h mice) prolonged survival and inhibited both tumor angiogenesis and PDAC microinvasion." (PMID 30659170, 2019). "The migration of neutrophils toward the tumor is mainly mediated by CXC-chemokines that bind to CXCR1 and/or CXCR2." (PMID 30691207, 2019). "In the heterozygous Cxcr2 knockout PKF2h mice, MPO+ neutrophils and CD11b+Ly-6G+ MDSCs significantly decreased in the tumor nest." (PMID 30659170, 2019). "Inhibition of CXCR2 in a mouse model of PDAC reduces neutrophil migration and delays tumor progression." (PMID 31474989, 2019). "We recently showed that CXCR2 expression is downregulated on tumor-infiltrating NK cells in RCC and genetic modification to re-express CXCR2 enhanced recruitment of NK cells to the tumor site." (PMID 30319622, 2018). "A CXCR2 antagonist suppresses MDSC infiltration and delays tumor growth in Snail-expressing mouse tumors." (PMID 29703902, 2018). "These cells express CXCR1 and CXCR2 at their surface and are recruited by their ligands including CXCL1 and CXCL2 which can be produced by tumor, endothelial cells or fibroblasts." (PMID 29983866, 2018). "Kershaw and colleagues have demonstrated that expression of CXCR2 improved T-cell migration in a melanoma tumor which produced CXCL1, a chemokine commonly secreted by tumor cells." (PMID 29872437, 2018). "Monocytic MDSCs, that include macrophages at different maturation stages, express CCR2, CXCR2 and CXCR4, and can reach the tumor via their specific ligands CCL2, CXCL5 and CXCL12 respectively." (PMID 30319638, 2018). "The important findings of this study are that IL-8 promotes tumor growth by both autocrine and paracrine mechanism by binding to its receptors CXCR1 and CXCR2 as deduced from protein localization by immunohistochemistry." (PMID 30086759, 2018). "T cells transduced to express chemokine receptors matching the TME chemokines can improve tumor homing after ACT, as shown by improved migration of tumor ascites lymphocytes to the EOC microenvironment by T-cell CXCR2 transduction." (PMID 30049987, 2018). "One dominant downstream effector pathway was the Cxcl1/Cxcr2 axis, as shown by inhibition of tumor growth by the Cxcr2 antagonist SB25002, and the inability of EO771/shCxcl1 cells to sustain tumor proliferation in syngeneic mice." (PMID 29632317, 2018). "Our results support a model where NRAS‐mutant, chemokine‐expressing circulating tumor cells target the CXCR1‐expressing lung vasculature and recruit CXCR2‐expressing myeloid cells to initiate metastasis." (PMID 28341702, 2017). "They classified ESCC tissues into two groups, negative and positive, based on the product of the intensity of immunostaining and the percentage of positive tumor cells expressing CXCL8 and CXCR2." (PMID 29285315, 2017). "Furthermore, CXCR2+ MDSCs could significantly aggravated tumor metastasis." (PMID 29383101, 2017). "In summary, our results established a critical role of tumor-derived TGF-β in triggering the influx of MDSCs into the liver through facilitating the interaction between the CXCL1/2/5 and the CXCR2." (PMID 28243237, 2017). "By binding to CXCR2, CXCL5 mediates various cellular behaviors including neutrophil trafficking, tumor cell migration and invasion." (PMID 28356111, 2017). "Ligands for the chemokine receptor CXCR2, on the other hand, are readily secreted by a variety of solid tumors, including RCC, to promote angiogenesis, tumor growth and metastasis." (PMID 28923105, 2017). "For example, tumor secrete ligands CCL5, CCL7, and CXCL8, bind to their receptors CCR1 or CXCR2 expressed on subtypes of MDSCs, and attract MDSCs in the tumor microenvironment." (PMID 29299180, 2017).
tumor (continued). "Blockade of IL-1 signaling was even more profound than CXCR2 antagonism at augmenting a growth inhibitory effect of MAPK inhibition in vivo and by itself had a marked effect on tumor growth." (PMID 28450382, 2017). "Expression of CTLA-4 and CXCR2 was the highest and among the highest for CSF1R expression within the TCGA HNSCC cohort compared to other tumor types." (PMID 28915554, 2017). "Activation of CXCR2 mainly induced the PI3K/Akt/GSK-3β/Snail signaling pathway and the subsequent epithelial- mesenchymal transition (EMT) to promote tumor cell invasion and metastasis." (PMID 29312644, 2017). "Primary tumor tissues and plasma from 14 RCC patients that underwent nephrectomy were evaluated for the presence of cognate ligands for the chemokine receptor CXCR2 by Bio-Plex chemokine array." (PMID 28923105, 2017). "In training set, clinicopathological materials analysis demonstrated that high-expression of CXCR2 in CRC samples was significantly correlated with Dukes stage (P = 0.027), tumor invasion (P = 0.031) and liver metastasis (P = 0.015)." (PMID 28415702, 2017). "CXCR1 and CXCR2 chemokine receptors and their ligands (CXCL1/2/3/7/8) play an important role in tumor progression." (PMID 28129639, 2017). "In the tumor nests of human ESCC tissues, various levels of CXCR1 or CXCR2 were observed: low and high compared to the normal squamous epithelia as a positive control." (PMID 29285315, 2017). "When 500 ng/ml CXCL1 antibody or 400 nM CXCR2 inhibitor SB225002 was added into CAF medium, SOD1 was significantly upregulated in tumor cells, suggesting CAF-secreted CXCL1 inhibited the expression of SOD1." (PMID 28518141, 2017). "This chemokine was also reported to activate the recruitment of bone marrow MSCs into diffuse-type gastric cancer stroma and the inhibition of migration in tumor microenvironment induced by the CXCR2 antagonist SB225002, decreases tumor volume and metastasis." (PMID 29081734, 2017). "Combined, these data indicate that ASCs are attracted by tumour-secreted CXCL1 synergistically acting through CXCR1 and CXCR2." (PMID 27241286, 2016). "Knocking-down CXCR2 in KRAS(G12D)-bearing human pancreatic duct-derived cells demonstrated a significant decrease in the in vitro and in vivo tumor cell proliferation." (PMID 26771140, 2016). "Recruitment to CXCL1-sh-RM1 tumours was also reduced by 2-fold for control ASCs and by 10-fold for CXCR1/CXCR2 knockdown ASCs." (PMID 27241286, 2016). "In contrast, the frequency of CXCR2+ cells was comparable for control-sh-RM1 and CXCL1-sh-RM1 tumours." (PMID 27241286, 2016). "Treatment of BT474 tumor cells in vitro with (ruxolitinib + afatinib) increased the expression of the IL-8 receptors CXCR1 and CXCR2 on the cell surface." (PMID 27379204, 2016). "This aggressive phenotype was attenuated in CXCR2 knockout mice, mechanistically linking enhanced NF-κB activity, CXCL1 expression, CXCR2-dependent leukocyte recruitment into the tumor microenvironment and aggressive in vivo phenotype." (PMID 26690220, 2015). "Further studies will be needed to identify combination partners for maximal benefits among various CXCR2 and VEGFR2 inhibitors, using an orthotopic and patient-tumor derived xenograft models of ovarian cancer." (PMID 26414070, 2015). "For example, it has been reported that expression of chemokine receptors CXCR2 and CCR2 by CAR modified T cells can facilitate their localization to the tumor site and hence antitumor immune responses." (PMID 25460506, 2015). "Thus, CD4+ T cells may also mediate upregulated expression of angiostatic chemokines such as CXCL9, CXCL10, and CXCL14 that are capable of inhibiting tumor growth or may downregulate expression of the chemokine receptor CXCR2 or its many ligands that promote angiogenesis." (PMID 26618181, 2015). "CXCR2+ and/or CCR2+ MDSCs are recruited to the tumor microenvironment by at least GM-CSF, CXCL1 and IL-8 chemotaxis." (PMID 26690220, 2015).
tumor (continued). "Further, up-regulation of CXCR2 is correlated with activated AKT signaling during the migration of lymphocytes and tumor progression of cancer cells." (PMID 26402907, 2015). "Interleukin-8 (IL-8) is a CXC-type chemokine that has multiple functions within the tumor microenvironment; promoting cell growth, invasion and metastasis of cancer cells through binding its receptors, CXCR1 and CXCR2 in an autocrine fashion." (PMID 24932473, 2014). "MDSCs are recruited into tumors via the chemokine GPCRs CCR2, CXCR2, or CXCR4 and are believed to promote tumor progression, such as facilitating metastasis in CRC." (PMID 25110692, 2014). "There is evidence that tumor angiogenesis can be stimulated by tumor cell secreted CXC chemokine ligands CXCL5 and CXCL8, via their common receptor CXCR2." (PMID 23531764, 2013). "Recently, Peng and his colleagues have shown that over-expression of the murine chemokine receptor CXCR2 on T cells improves their homing to melanoma and tumor regression in mice model, suggesting that endowing T cells with improved chemotaxis capabilities to tumor sites may also enhance ACT." (PMID 22778766, 2012). "Although CXCR2-dependent senescence dramatically inhibits the tumor growth of hPTTG1-overexpressing MCF-7 cells, hPTTG1-induced SASP remodels the tumor microenvironment to promote the metastasis of neighboring nonsenescent cancer cells." (PMID 22789011, 2012). "It is thus possible that tumor cells up-regulate IL-8 to compensate for the reduced VEGF activity, which in turn exploits both the angiogenic CXCR2 pathway, as well as indirectly transactivating the angiogenic VEGFR2 pathway." (PMID 23029099, 2012). "Intermediate to strong expression of CXCL1, CXCR1 and CXCR2 was concurrently detected in the epithelium of stage II and stage III CRC tumours." (PMID 21285972, 2011). "There was significantly increased expression of CXCR2, CXCR3, and CCR1 in the tumour islets of ES compared with PS patients [median 6.5 versus 2.6, (p = 0.007), 12.7 versus 3.2, (p = 0.01), and 24.3 versus 2.4 cells/mm2, (p = 0.002), respectively]." (PMID 20429924, 2010). "There was increased expression of CXCR2, CXCR3, and CCR1 in the tumour islets of ES compared with poor survival (PS) patients (p = 0.007, 0.01, and 0.002, respectively)." (PMID 20429924, 2010). "In mouse models, neutralization of CXCR2, the principle receptor for KC and MIP-2 reduces PMN infiltration as well as tumor growth and angiogenesis, suggesting a role in tumor progression." (PMID 20385015, 2010). "We used immunohistochemistry to identify cells expressing CXCR1, CXCR2, CXCR3, CXCR4, CXCR5 and CCR1 in the tumour islets and stroma in 20 patients with surgically resected NSCLC." (PMID 20429924, 2010). "CXCR2 chemokine ligands CXCL1, CXCL5 and CXCL6 were shown to be involved in chemoattraction, inflammatory responses, tumor growth and angiogenesis." (PMID 18578857, 2008). "Likewise, CXCR1 or CXCR2 expression enabled CAR-T cells to follow tumor-derived IL-8 signals, improving migration and tumor control." (PMID 41596556, 2026). "Our data indicated that blockade of CXCR2 or CFB efficiently prohibited Dox-induced NET generation and enhanced chemotherapy effects, leading to markedly decreased tumor growth." (PMID 41480760, 2026). "We also examined the expression of CD38, CD33, and CXCR2 in tumor tissues of TE10 tumor-bearing hu-HSC-NOG-EXL mice treated with AZD4547 10 mg/kg for 21 d and AZD4547 treatment significantly reduced the CD38, CD33, and CXCR2 levels in tumor tissues." (PMID 40722739, 2025). "AZD5069 reduced the mRNA of CXCR2, the cognate CXCL8 receptor, in normal and tumour thyroid cells." (PMID 38900374, 2025). "Chemokines including CXCL5/CXCR2 are essential for MDSC recruitment in 4T1 BALB/c murine tumor models, while CCL1, CCL2, CCL5, GM-CSF, and G-CSF facilitate MDSC expansion and aggregation in the tumor milieu." (PMID 40909271, 2025). "In CXCR2 signaling, Gαi-GTP suppresses cAMP-PKA pathways to drive tumor invasion." (PMID 40552145, 2025).